MYC (MYC proto-oncogene, bHLH transcription factor)
Diseases named in the same sentence as MYC in open-access papers (continued):
Sharing a sentence is not in itself a finding about the gene and the disease.
breast cancer (continued). "Though it provided some information, the detection method of MYC expression was very different from that today and the number of included studies with prognosis of breast cancer patients was small." (PMID 29212204, 2017). "In summary, this study provides the first evidence that TIM promotes aggressive progression of breast cancer through upregulation of MYC, contributing to the poor prognosis of patients with breast cancer." (PMID 28464854, 2017). "A lot of clinical researches published before have investigated MYC expression and related signal pathway in breast cancer cells and patients, and discovered strong correlation between MYC overexpression and breast cancer progression." (PMID 29212204, 2017). "HR of FISH and other technique subgroups in 7 studies (8 cohorts) displayed a poor prognosis of high MYC expression in breast cancer patients, however, the technique of IHC and Genechip (5 studies/ 8 cohorts) showed a negative prognosis of MYC overexpression." (PMID 29212204, 2017). "We found a significant inverse correlation between MYC and p27 levels in breast cancer, which was particularly strong if looking at tumors with high p27 levels concomitant with low levels of phosphorylation at Threonine 157 (Thr-157)." (PMID 28665315, 2017). "Overall, HN1 promoted MYC migration, invasion, and tumorigenesis of breast cancer and the self-renewal of BCSCs through upregulating MYC expression." (PMID 28490334, 2017). "Further gene expression profiling analysis revealed that p62 was positively correlated with MYC expression level, which mediated the function of p62 in promoting breast cancer stem-like properties." (PMID 27345399, 2017). "MYC, one of the most studied oncogenes, is typically overexpressed in variety of malignant tumors such as lung cancer, lymphomas, breast cancer, gastric cancer, and colon cancer and is involved in cell proliferation, differentiation, apoptosis and cell cycle." (PMID 28056099, 2017). "It has been proposed that ETS2, a member of the ETS transcription factor family which is highly abundant in mammary tissues, cooperates with MYC in the regulation of TERT promoter activity in breast cancer cells." (PMID 28978027, 2017). "By combining the data on TERT gain and MYC overexpression we were able to isolate a particularly bad prognosis subgroup of breast cancer patients." (PMID 29100407, 2017). "Similar effects of a decreased glucose uptake and a diminished expression of GLUT 1 after incubation with the c-MYC inhibitor or after knockdown of c-MYC with siRNA were already described in breast cancer cells." (PMID 28724379, 2017). "We chose to investigate intratumoral genetic heterogeneity using c-MYC, since the c-MYC locus (8q24) is in one of the most unstable chromosomal regions and displays frequent copy number gain or amplification in all subtypes of breast cancer." (PMID 29228597, 2017). "In the past 20 years, there was only one published meta-analysis about MYC and prognostic and clinicopathological significance of breast cancer in 2000." (PMID 29212204, 2017). "c-MYC protein was upregulated in both breast cancer cell lines with RPL5 knockdown in vitro and in MDA-MB-231 tumors in vivo but downregulated in MCF7 tumors." (PMID 28147343, 2017). "Towards this goal, c-Myc amplification in a genetic model of PIK3CA-related breast cancer was discovered to circumvent PI3K-targeted treatment, in agreement with the observation that high MYC levels aligned with mutation of PIK3CA in patient samples." (PMID 28381598, 2017). "MYC mRNA level was reduced upon p62 deletion by siRNA and increased with p62 overexpression in breast cancer cells, suggesting that p62 positively regulated MYC mRNA." (PMID 27345399, 2017). "To mechanistically determine exactly how MYC/RAS co-operativity contributes to stemness in breast cancer cells, we used MCF7 cells as a model system." (PMID 29080556, 2017).
breast cancer (continued). "Accordingly, MYC is central to the core interactome in metastatic breast cancer patients, and stable MYC knockdown decreases colony formation at secondary organs." (PMID 28757546, 2017). "In MYC overexpressing breast cancer cell lines, inhibition of MAP3K13 leads to impaired colony formation in vitro and tumour regression in vivo, warranting further investigation of this synthetic dose lethal pair in melanoma." (PMID 28097822, 2017). "Glutamine dependence has been linked to various oncogenes including MYC, RAS, IDH and hormone receptor status in breast cancers." (PMID 28826492, 2017). "To conclude, we have shown that high Shannon indices of c-MYC and FGFR1 copy number variation are associated with adverse features of breast cancer." (PMID 29228597, 2017). "To further confirm a role of MYC for the p62-mediated stem-like properties in breast cancer, we conducted lentivirus-mediated MYC ectopic overexpression in both WT-MCF-7 and EpiR-MCF-7 cells." (PMID 27345399, 2017). "To address these issues, we investigated the mutational status and genotype of the TERT promoter, TERT gene copy number and TERT and MYC mRNA expression in two breast cancer cohorts." (PMID 29100407, 2017). "This includes 7 out of 1757 enhancer/super enhancer nodes harboring breast cancer SNPs, one of which is a super enhancer and targets the promoter of the MYC oncogene that is constitutively expressed in many cancers, including breast and blood cancers." (PMID 29089515, 2017). "MYC is considered to promote tumor cell survival, proliferation and progression in breast cancer and regulates the expression of 13 different poor-outcome cancer signatures." (PMID 29100407, 2017). "Among the 14-3-3 proteins, 14-3-3σ is capable of enhancing ubiquitination and degradation of MYC, and functions as a key regulator of cell metabolism in breast cancer cells." (PMID 28362357, 2017). "Studies have shown that GADD45A exhibits context-dependent effects, in that it stimulates proliferation in MYC-driven breast cancers but induces apoptosis and senescence in Ras-driven breast cancers." (PMID 28235006, 2017). "In human breast cancer, MYC is amplified and overexpressed in 12 to 100% of cases and is associated with an aggressive phenotype." (PMID 28418910, 2017). "In short, this meta-analysis implies that high MYC expression in breast cancer is related to poor prognosis of patients, especially to patients with negative ER and PR." (PMID 29212204, 2017). "Approximately 10% of all human breast cancers show co-amplification of MYC and PVT1, with a particularly high proportion (62%) among HER2+ tumors." (PMID 28430642, 2017). "In breast cancer cells, MYC binds to an ETS2 site (EtsA) in the TERT gene promoter and increases TERT expression levels." (PMID 29100407, 2017). "MTI-31 in combination with etomoxir, a fatty acid oxidation inhibitor, suppresses the MYC protein level and cell growth in breast cancer cells." (PMID 28362357, 2017). "CCI-779 also inhibits MYC protein expression in breast cancer cells with a decrease in the phosphorylated protein level of 4EBP1." (PMID 28362357, 2017). "The H3K79 methyltransferase DOT1L promotes breast cancer metastasis by activating many EMT mediators in collaboration with c‐MYC." (PMID 27756687, 2017). "In the present study, we demonstrate that high expression of TIM contributes to maintenance of the CSC population, migration, invasion and tumorigenicity of breast cancer through activation of MYC." (PMID 28464854, 2017). "With the increase in our knowledge of aurora kinases, nuclear AURKA has been found to bind to hnRNP K, acting as a transactivating factor to activate the expression of MYC and promoting breast cancer." (PMID 28595628, 2017).
breast cancer (continued). "Our results showed that high MYC expression was associated with worse DFS/RFS and OS for breast cancer patients." (PMID 29212204, 2017). "Previous independent reports have shown the overexpression of CCAT2 in breast cancer tissues, as well as overexpression of MYC in certain types of breast cancer." (PMID 28480695, 2017). "Confirming the cell-type specificity, levels of these markers of active chromatin were low in MCF-7 breast cancer cells that lack both HIF-α binding at the SNP-associated site and regulation of MYC or PVT1 RNA by hypoxia." (PMID 27774982, 2016). "The results suggested KDM3A/JMJD1A regulates the tumorigenesis of breast cancer through down-regulating H3K9me2 on oncogenes MYC and PAX3." (PMID 27034728, 2016). "MYC protein, including c-Myc, N-Myc and L-Myc, have been shown to be involved in pathogenesis of most cancers, such as burkitt’s lymphoma, breast cancer, prostate cancer, gastrointestinal cancer etc.." (PMID 26817819, 2016). "Univariate and multivariate analyses showed that low nuclear ADA3 staining or high c-MYC expression independently predict poor survival in ER+ breast cancers." (PMID 27852327, 2016). "For example, the L-FFL motif comprised of MYC, miR-98 and LINC00665 correlated with breast cancer patient survival (P=0.023), in agreement with previous studies showing that MYC and miR-98 correlate with cancer patient survival." (PMID 27322142, 2016). "Here the authors show that in breast cancer cells Aurora kinase A has a kinase-independent function in the nucleus by activating the MYC promoter in cooperation with hnRNP K, enhancing the breast cancer stem cell phenotype." (PMID 26782714, 2016). "Although almost invariably SQLE and MYC loci presented identical or near similar log2 ratio values (ρ = 0.96 in breast cancer and 0.89 in ovarian cancer, D bottom right), SQLE and MYC transcripts were not correlated with each other (D bottom left)." (PMID 26777065, 2016). "Tumors were induced in 6-week old mice and after appearance of palpable mammary tumors, a subset of mice were withdrawn from doxycycline to inhibit MYC expression." (PMID 27590350, 2016). "Analysis of breast cancer tissue specimens showed a significant correlation of ADA3 nuclear expression with c-MYC expression." (PMID 27852327, 2016). "The correlation between cyclin B1 and MYC gene copy number was also observed in clinical breast cancer samples, supporting the role of MYC in regulating cyclin B1 expression." (PMID 27486754, 2016). "Integrin αVβ3 expression contributes breast cancer cell migration and metastasis since exogenous expression of integrin αVβ3 in human breast cancer cells rescues the invasiveness and migration that are suppressed by MYC." (PMID 27145276, 2016). "Among the genes analyzed, MYC is the most strongly repressed by E1A 1-80 C+ in the breast cancer cell lines tested." (PMID 27382434, 2016). "c-MYC plays a key role in breast cancer, with gene amplification seen in approximately 15% cases and its overexpression associated with poor outcomes." (PMID 27852327, 2016). "Analysis of a large cohort of 588 breast cancer tissue specimens showed a significant correlation of ADA3 nuclear expression with c-MYC expression." (PMID 27852327, 2016). "The height of this recurring amplicon included mean log2ratios >4 consistent with amplification of genomic drivers such as HER2 and MYC described in breast cancer and other solid tumor genomes." (PMID 26317899, 2015).
breast cancer (continued). "Taken together, these data indicate that c-MYC copy number gain is more common in radiogenic breast cancer than in sporadic disease, and that a greater proportion of radiogenic samples have c-MYC copy number gains that affect specifically the c-MYC locus." (PMID 25531321, 2015). "Specifically, we characterized associations between haplotypes in LD with human NDN and the expression level of c­-MYC in TCGA breast cancer cohort." (PMID 26384308, 2015). "In this study, loss of SAE2 led to apoptosis, mitotic spindle defects, and reduced tumor growth in MYC-dependent breast cancer cells." (PMID 25860128, 2015). "In summary, these data demonstrate that c-MYC expression is higher in radiogenic breast cancer compared with sporadic disease." (PMID 25531321, 2015). "There was a higher c-MYC to centromere 8 ratio in radiogenic breast cancer compared with sporadic breast cancer (Mann–Whitney U-test, P=0.016)." (PMID 25531321, 2015). "Taken together, these data identify c-MYC as a radiosensitive locus, implicating this oncogenic transcription factor in the aetiology of radiogenic breast cancer." (PMID 25531321, 2015). "This is supported by recent in vitro and in vivo studies that show that ERBB2 and MYC can cooperate to induce aggressiveness in breast cancer." (PMID 26018524, 2015). "Our study has clearly demonstrated an association between antecedent radiation exposure and elevated expression of c-MYC in breast cancer." (PMID 25531321, 2015). "This noting is supported by the fact that CCND1 amplification is strongly linked to hormone receptor (ER/PR) positive breast cancers, while HER2 and/or MYC (like PTEN deletions in our study) are more often found in ER-negative than in ER-positive cancers." (PMID 26672755, 2015). "In breast cancer cell lines, neratinib and docetaxel show a synergistic effect specific for the MYC-amplified line." (PMID 26018524, 2015). "Comparison of copy number analysis of HMEC, SUM149PT, SUM1315MO2 adherent cells revealed high copy numbers of AKT1, AURKA, CDK4, EGFR1, PAK1 and MYC in breast cancer cells as compared to HMEC cells." (PMID 26608463, 2015). "In human breast cancers, up to 80% of MYC-amplified triple negative breast cancer (TNBC) cases harbor MCL1 co-amplification." (PMID 25784482, 2015). "The fact that we observed a higher proportion of the malignant than benign mammary tumours with recurrent amplification in the region of MYC correlates well with the known involvement of MYC in human breast cancer." (PMID 25955013, 2015). "A recent publication outlined a role for BRD-mediated transcription of MYC in tamoxifen-resistant breast cancers." (PMID 25537515, 2015). "PFDN5 has been described to repress c-MYC and is, therefore, a candidate tumor-suppressor and cancer-driver gene in canine mammary cancer." (PMID 26132936, 2015). "Detailed single-cell analysis also revealed considerable intra- and intertumour heterogeneity with respect to c-MYC copy number in human radiogenic breast cancer, suggesting continuous evolution at this locus during disease development and progression." (PMID 25531321, 2015). "For example, BCL2, NFkB (RELA), XBP1, HSP5A/GRP78 MYC are known to be overexpressed in breast cancer cells or tumors that are resistant to antiestrogens." (PMID 25693144, 2015). "There was a trend towards higher expression of c-MYC in the radiogenic breast cancer compared with sporadic breast cancer (Mann–Whitney U-test, P=0.119)." (PMID 25531321, 2015). "Dual hybridisation analysis of these four c-MYC-amplified cases demonstrated that the magnitude of c-MYC copy number gain was higher in the radiogenic breast cancers compared with the sporadic cancers." (PMID 25531321, 2015).
breast cancer (continued). "Given the established role of c-MYC in breast cancer pathogenesis, the aetiology and evolution of this alteration was investigated in cells that had received a cumulative radiation dose of 20, 40, 60 and 80 Gy." (PMID 25531321, 2015). "Meta-analysis of over a thousand primary breast cancers showed that high VEGF expression is strongly associated with STAT3 and MYC expression, supporting the link between VEGFR-2 and CSC self-renewal." (PMID 26500608, 2015). "Intriguingly, however, we observed a modest, yet highly significant positive correlation between FBXW7 and MYC expression, exclusively in the Luminal A-subtype of breast cancers (rho=0.28, p=0.0004)." (PMID 25669969, 2015). "c-MYC copy number was higher in radiogenic compared with sporadic breast cancer (Mann–Whitney U-test, P=0.027)." (PMID 25531321, 2015). "This combination also shows MYC-dependent synergistic interaction in lung cancer and breast cancer cell lines, similar to the combination of neratinib and GSK-1070916." (PMID 26018524, 2015). "This is in contrast to cells derived from breast cancer types with MYC overexpression, which can be unresponsive to MYC suppression." (PMID 25669969, 2015). "In concordance with our findings, a recent work has shown that both CIP2A and SET are frequently co-overexpressed with c-MYC in breast cancer cell lines." (PMID 25726524, 2015). "In support of this supposition, recurrent amplification of the c-MYC locus has been reported in breast cancers that developed in atomic bomb survivors." (PMID 25531321, 2015). "Among the recurrent gene amplifications were oncogenes PIK3CA and MYC, also known to be frequently amplified in breast cancers." (PMID 25970776, 2015). "We determined c-MYC protein expression in radiogenic and sporadic breast cancers by immunohistochemistry and derivation of a histoscore." (PMID 25531321, 2015). "Our data also demonstrate extensive intratumor heterogeneity with respect to c-MYC copy number in radiogenic breast cancer, suggesting continuous evolution at this locus during disease development and progression." (PMID 25531321, 2015). "Our findings show that MYC-driven pro-survival signaling in antiestrogen resistant breast cancer is partially dependent on proteins that control the cell cycle and apoptosis." (PMID 25339305, 2014). "It is important to point out the MYC expression is frequently deregulated in cancer cells; indeed, its expression is increased in a wide variety of human cancers, including 80% of breast cancer, 70% of colon cancer, and 50% of hepatocellular carcinomas." (PMID 24589226, 2014). "In this study, we identified MYC, an oncoprotein that is upregulated in endocrine resistant breast cancer, as a regulator of the UPR in glucose-deprived conditions." (PMID 25339305, 2014). "miR-24 is transcriptionally upregulated in breast cancer with lymph node metastasis in part by MYC, and overexpression of miR-24 in MCF-7 breast cancer cells promotes invasion and metastasis through repression of SPRY2 and subsequent MAPK activation." (PMID 25364765, 2014). "c-MYC, as a well-known estrogen-responsive gene, has been shown to mediate the proliferative effects of estrogen in ER+ breast cancer cells." (PMID 24735615, 2014).